ALB (albumin)
Diseases named in the same sentence as ALB in open-access papers (continued):
Sharing a sentence is not in itself a finding about the gene and the disease.
systemic inflammatory response syndrome (28 papers, 2014 to 2025). SIRS is a serious condition related to systemic inflammation, organ dysfunction, and organ failure. "Low ALB serum levels may be associated with systemic inflammatory response syndrome." (PMID 34631892, 2021). "Existing literature underscores the significance of serum albumin in relation to systemic inflammatory response syndrome, aspiration pneumonia, and three-month mortality." (PMID 39003396, 2024). "Decreased postoperative serum albumin levels is closely related to systemic inflammatory response syndrome, triggering increased fractional synthesis and pathological capillary leakage of serum albumin." (PMID 36386497, 2022). "Albumin is particularly indicated for patients who develop systemic inflammatory response syndrome (SIRS) or sepsis due to its endothelial-stabilizing attributes in addition to its volume-expanding properties." (PMID 30930689, 2019). "The ratio reflects two important pathophysiological processes: the level of CRP indicates the degree of systemic inflammatory response syndrome due to infection, while the level of ALB reflects nutritional status, hepatic synthetic function, and the degree of an underlying catabolic condition." (PMID 41426582, 2025). "Studies have found that some patients with severe systemic inflammatory response syndrome may have decreased serum albumin levels, and the degree of change is related to the prognosis of the disease." (PMID 35071771, 2021). "Low albumin levels in oncologic disease might be secondary to the intense systemic inflammatory response syndrome, which requires an increased synthesis of acute-phase proteins, reducing the synthesis of other proteins, such as albumin." (PMID 33672318, 2021). "Similarly, a reduction in albumin levels after surgical trauma is related to generalized inflammation, or systemic inflammatory response syndrome, which is characterized by increased capillary leakage of albumin." (PMID 32664910, 2020). "Increased capillary leakage of albumin is one of the features of systemic inflammatory response syndrome (SIRS), which leads to low plasma albumin levels in patients undergoing major abdominal surgery." (PMID 28069031, 2017). "Sequential Organ Failure Assessment (SOFA) score; systemic inflammatory response syndrome score; white blood cell count; and serum C reactive protein, procalcitonin (PCT), interleukin-6 (IL-6), lactate, albumin, and hemoglobin levels were recorded." (PMID 25460569, 2014). "In multivariate analysis, albumin < 38.5 g/L (OR: 16.53), CALLY index < 0.45 (OR: 6.40), and systemic inflammatory response syndrome (SIRS) detection (OR: 12.98) were determined as independent factors predicting the Hartmann procedure." (PMID 40870500, 2025).
Thrombocytosis (28 papers, 2011 to 2025). Increased numbers of platelets in the peripheral blood. "In this study, we investigated the association between relative thrombocytosis and an increased urine albumin-to-creatinine ratio in healthy adult participants." (PMID 38248790, 2024). "Low haemoglobin, lymphadenopathy, thrombocytosis, low albumin, and raised C reactive protein in younger men also had PPVs of ≥3%." (PMID 39414353, 2024). "For patients aged 40-49 years, PPVs ≥3% were observed for thrombocytosis, low albumin and haemoglobin, and raised alkaline phosphatase and C reactive protein, and in men for raised erythrocyte sedimentation rate and white cell count." (PMID 39414353, 2024). "Thrombocytosis, low albumin and haemoglobin, and raised C reactive protein in younger men also had PPVs ≥3%." (PMID 39414353, 2024). "Albumin (37.19 ± 4.73 g/L vs 39.67 ± 3.99 g/L, p = 0.001) and hemoglobin (122.88 ± 17.25 g/L vs 131.51 ± 16.03 g/L, p = 0.002) were lower in thrombocytosis group compared with non-thrombocytosis group." (PMID 36922788, 2023). "NLR and other similar indicators, such as C-reactive protein, albumin, the Glasgow prognostic score, thrombocytosis and PLR may reflect systemic inflammation." (PMID 28392554, 2017). "Typically there are also laboratory abnormalities: elevated serum concentration of gamma globulin and acute phase proteins, thrombocytosis, elevated ESR, low serum albumin level, proteinuria, and, sometimes, elevated IL-6, especially in the plasma cell systemic disease." (PMID 22014148, 2011).
ulcer (28 papers, 2005 to 2026). "Furthermore, in these patients, infections caused by ulcers and necrotic lesions may be responsible for low serum albumin levels, and ischemic pain may be indirectly related to a decrease in oral intake." (PMID 35082938, 2021). "The Lasso regression process highlighted treatment, ulcer location, hemoglobin, creatinine, the proportion of the decaying area, Body Mass Index (BMI), disease duration, albumin, and the ankle-brachial index as critical variables." (PMID 37663260, 2023). "Based on the MS intensities of serum fibrinogen and albumin, we, therefore, clearly differentiate gastritis cases from other gastroduodenal afflictions, including ulcers and GC." (PMID 35566209, 2022). "As consistent with previous researches, our study also indicated that a higher level of ALB was facilitated to ulcer healing." (PMID 33143666, 2020). "The antiulcer and in vitro anti-inflammatory activities of the aerial parts of Enicostemma littorale against aspirin, ethanol, and pyloric ligation-induced ulcers in rats and bovine serum albumin denaturation were studied." (PMID 21264096, 2010). "Parameters such as ulcer grade and serum albumin offer valuable insights into healing potential." (PMID 40821188, 2025). "HGB, ALB, and LRG were significantly linked to ulcer presence, with LRG achieving the highest AUC." (PMID 40276148, 2025). "It was reported that ALB was a simple biomarker of wound healing in patients suffering from ulcers." (PMID 33143666, 2020). "Age (>59.5 years), lack of attempted soft tissue coverage, haemoglobin (<111g/L) and albumin (<25g/L) were associated with non-healing ulcers (p=0.003)." (PMID 32455097, 2020). "Age at diagnosis, ulcer recurrence, atopic dermatitis history, white blood cell count, blood eosinophil count, platelet count, serum albumin level, iron level, erythrocyte sedimentation rate, and C-reactive protein level differed significantly among the 5 groups (all p < 0.05)." (PMID 32819298, 2020). "Among them, HGB and ALB were significantly lower, and LRG was significantly higher in sessions with an ulcer." (PMID 40276148, 2025). "Data were collected on demographics, ulcer severity (Wagner Grade), glycemic status (HbA1c), biochemical markers (C-reactive protein [CRP], interleukin-6 [IL-6], tumor necrosis factor-alpha [TNF-α], and serum albumin), and clinical outcomes." (PMID 40821188, 2025). "There were significant differences in C-reactive protein, erythrocyte sedimentation rate, fecal calprotectin, albumin, maximum bowel wall thickness, and length of disease between patients without and with radiologic ulcers (P < 0.05)." (PMID 39292244, 2024). "There were significant differences in CRP (P = 0.01), erythrocyte sedimentation rate (P = 0.008), fecal calprotectin (P = 0.01), and albumin (P = 0.02) between patients without and with radiologic ulcers." (PMID 39292244, 2024). "Regarding laboratory factors, WBC counts (p = 0.008), eosinophil counts in blood (p = 0.013), platelet counts (p < 0.001), serum levels of albumin (p = 0.027), iron (p < 0.001), ESR (p < 0.001), and hsCRP (p = 0.016) differed significantly among the 5 ulcer groups." (PMID 32819298, 2020). "In addition to ulcer severity and infection, we examined the correlation between fibrinogen and clinical parameters, uncovering significant relationships with CRP, fasting blood glucose, and serum albumin." (PMID 40151482, 2025). "Recent studies have highlighted the importance of albumin levels in predicting DFU risk, with significant correlations between reduced albumin levels and heightened risks of severe complications, including non-healing ulcers." (PMID 39409014, 2024).
uremia (28 papers, 2008 to 2025). A clinical syndrome associated with the retention of renal waste products or uremic toxins in the blood. "The inverse IS–albumin correlation could be due to proteinuria-led albumin loss; additionally, low albumin levels or uremia-induced structural modifications of albumin might impair the clearance of protein-bound IS, increasing circulating free IS." (PMID 40559861, 2025). "Therefore, we consider that a reasonable prescription setting in the A-MPD mode is of great importance, considering both the albumin loss and rapid alleviation of the uremia status." (PMID 37313750, 2023). "We observed that patients undergoing renal replacement therapy with hemodialysis for longer durations are exposed to inflammation, uremia, and low albumin levels." (PMID 40244253, 2025). "It has already been shown that both fatty acids and toxins accumulating in uremia have an influence on the binding between furosemide and albumin." (PMID 36556982, 2022). "The deterioration of ABiC is negatively correlated with the serum concentration of indoxyl sulfate, a toxin that accumulates in uremia and is present in the plasma, primarily in albumin-bound form." (PMID 36556982, 2022). "The measured mean differences for parameters that are known to be altered in uremia, such as hemoglobin, hematocrit, serum creatinine, albumin and total proteins, were statistically significant in CKD patients compared to healthy subjects (CTRL)." (PMID 33802652, 2021). "In another investigation, we found that serum albumin drawn from an animal model of uremia also renders macrophages vulnerable to endoplasmic reticulum stress and disturbs reverse cholesterol transport by impairing the ABCA1 expression and activity." (PMID 33019603, 2020). "These mice exhibited uremia within 4–6 weeks, which correlated with the excretion of albumin in the urine." (PMID 26412304, 2015). "The NEWS2 cut-off ≥ 8 in combination with low albumin and uremia improved predictive-accuracy, and could be easily used in general practice." (PMID 36828485, 2023). "As an example, the binding of calcium to albumin has been found to decrease in uremia." (PMID 27631369, 2016). "However, the longer half-life and volume of distribution of isavuconazole in individuals with ESRD may also be due to decreased plasma binding by albumin due to uremia which may impact drug metabolism by the liver." (PMID 28271239, 2017). "Only SAA1, albumin, phospholipase A2 and apoC-III were differentially expressed between HDL from controls and those with uremia." (PMID 32921312, 2020). "Uremia promotes protein catabolism, increases the generation of non-nutritional toxins, and decreases albumin levels." (PMID 37304869, 2023).
abscess (27 papers, 2016 to 2026). An inflammatory process characterized by the accumulation of pus within a newly formed tissue cavity which is the result of a bacterial, fungal, or parasitic infection or the presence of a foreign body. "It is important to note that low albumin, weight loss, older age, preoperative steroid therapy, and the presence of abscess or fistula at the moment of strictureplasty increase the risk of intra-abdominal septic adverse events." (PMID 37176493, 2023). "A low PWR, old age, male sex, abscess size, albumin, ALP and unidentified causative pathogens showed significant associations with a hospital stay longer than 28 days." (PMID 36292245, 2022). "The risk factors for requiring hospitalization for more than 28 days were a low PWR, older age, male sex, size of the abscess, levels of albumin and ALP and infection with unidentified causative pathogens." (PMID 36292245, 2022). "In a recent meta-analysis, steroid use, low albumin level, preoperative surgical history, and preoperative abscess were retained as risk factors for adverse surgical outcome." (PMID 28587182, 2017). "Risk factors for septic metastases include septic shock at admission, low platelet count, low albumin, high levels of C-reactive protein (over 200 mg/L), and abscesses larger than 6 cm, as reported in a case-controlled study in Singapore." (PMID 40564854, 2025). "Demographics, comorbidities, laboratory markers (CRP, ESR, ALP, albumin), radiological findings (abscess presence, anatomical location, claw sign), prior antibiotic use, and microbiological results were analyzed." (PMID 41010981, 2025). "There is information about preoperative albumin levels in six out of ten patients with postoperative abscesses during the COVID-19 pandemic." (PMID 38337344, 2024). "Biochemical data suggests low mean hemoglobin (9.2±0.63 g/dL vs 10.46±1.34 g/dL, p=0.004), low albumin (2.72±0.35 g/dL vs 3.52±0.34 g/dL, p<0.001), increased prothrombin time (23.37±6.35s vs 14.15±2.34s, p=0.002) in ruptured abscesses." (PMID 39493166, 2024). "In the univariate analysis, factors associated with excessive intraoperative blood loss included prior abdominal surgery, prior pancreatic pseudocyst/abscess, preoperative albumin, PT, APTT, intraoperative transfusion, and preoperative SAE." (PMID 34537854, 2022). "PNI < 45, calculated with serum albumin (Alb) and total lymphocyte count, and larger cumulative abscess volume (CAV) measured by computed tomography seem outcome predictors." (PMID 36316935, 2022). "Our previous study found that the larger abscess always accompanies with higher leukocytes, lower albumin, and longer time for temperature normalization." (PMID 34917645, 2021). "In a recent study, large abscess volume (>500 mL or >10–8 cm), low albumin level, and high alkaline phosphatase level were significantly (P < 0.05) associated with failure of medical treatment of ALA." (PMID 31832547, 2019). "The size of abscess was correlated with leukocytes increase, albumin decrease, and time duration for body temperature normalization (all p < 0.05)." (PMID 27775098, 2016). "Additionally, postoperative abdominal complications such as intra-abdominal fluid collections or abscesses, low preoperative albumin levels, and the use of proton pump inhibitors have been identified as independent risk factors for DGE." (PMID 39458155, 2024). "For patients who were hospitalized for more than 28 days, the univariate logistic analysis revealed that a low PWR, older age, male sex, abscess size, levels of albumin, ALT, and ALP, infection with K. pneumoniae and unidentified infection were associated with prolonged hospitalization." (PMID 36292245, 2022). "However, patients with larger abscess exhibited significantly higher white blood cell count but lower albumin level (p = 0.013, and p = 0.002, respectively)." (PMID 27775098, 2016).
abscess (continued). "Biochemical parameters like low albumin raised total leucocyte count (TLC), increased prothrombin time, and large size of the abscess were predictors of ruptured abscess (p<0.001)." (PMID 39493166, 2024). "In human studies, decreased albumin and total antioxidant capacities were found in wound fluids, while neopterin concentrations (an antioxidant marker) were over 100 times higher in abscess pus, suggesting oxidative stress pathways may be involved with wound processes." (PMID 37174585, 2023). "APACHE II score, ALB, smoking, alcohol consumption, CAP, septic shock, ARDS, abscess and initial antimicrobial regimens were significantly associated with 30-day mortality." (PMID 37626308, 2023). "Univariate analysis showed that APACHE II score, ALB, GLU, PT, APTT, CAP, cardiovascular disease, abscess, hepatic abscess, extrahepatic lesion involved and multiple pathogens were significantly associated with ARDS." (PMID 37626308, 2023). "Then, we compared the levels of albumin, erythrocyte sedimentation rate (ESR), and C-reactive protein (CRP) at abscess diagnosis and at operation in both groups of patients who underwent surgery later." (PMID 28947899, 2017). "(iv) The absence of surgery when indicated, albumin level at admission, abscess formation, and systemic embolism were the independent predictors of in-hospital all-cause mortality." (PMID 36161622, 2022).
alcohol abuse (27 papers, 2012 to 2025). The use of alcoholic beverages to excess, either on individual occasions ("binge drinking") or as a regular practice. "The results indicated that lower P2Y12 gene promoter DNA methylation increased the risk of clopidogrel resistance in patients with albumin ≤35 g/L, current smoking, or alcohol abuse." (PMID 27686864, 2016). "It became clear to us that a significant association existed in the subgroup of Albumin < 35, current smoking, and alcohol abuse in the present study (to 5)." (PMID 24745016, 2014). "In summary, our study indicates that lower P2Y12 gene promoter DNA methylation increases the risk of clopidogrel resistance in the patients with Albumin ≤ 35, current smoking, or alcohol abuse." (PMID 24745016, 2014). "However, we found that a significant association existed in the subgroup of Albumin <35, current smoking, and alcohol abuse." (PMID 24745016, 2014). "These include low serum albumin (<30 g/L), C-reactive protein >100 mg/L, platelet count >400 × 109/L, serum sodium <130 mmol/L, IV drug use, and chronic alcohol abuse." (PMID 40519425, 2025). "People living with HIV and those diagnosed with alcohol use disorders (AUD) relative to healthy individuals commonly have low levels of serum albumin, substantiated as an independent predictor of cardiovascular events." (PMID 38824150, 2024). "Risk factors associated with this type of surgery include advanced age, male sex, higher BMI, longer smoking history, low serum albumin, pulmonary comorbidity, alcohol abuse, and low preoperative metabolic equivalents." (PMID 38213352, 2023). "Consequently, management should include targeted interventions to address alcohol abuse and aggressive nutritional support to optimize serum albumin levels upon admission and throughout treatment." (PMID 41384024, 2025). "In our case, the patient had a long history of alcohol abuse and presented with albumin and prealbumin at admission of 1.8 and 10.2, respectively, which could have predisposed the patient to bacterial seeding of the retrosternal hematoma." (PMID 39703264, 2024). "According to univariate Cox regression, the following indicators were significantly associated with development of HCC: age, sex, alcohol use disorder, DAA treatment, platelet count, serum albumin levels, bilirubin concentration, INR, LSM, delta-LSM, FIB-4 score and delta-FIB-4 score." (PMID 38664813, 2024). "Alcohol consumption behaviors and alcohol use disorder risk and presentation differ by sex, and are associated with blood concentrations of the steroid sex hormones, testosterone and estradiol, and their regulatory binding proteins, sex hormone binding globulin (SHBG) and albumin." (PMID 40766921, 2025). "In a sample of 160 individuals with alcohol use disorder (AUD), 142 infected with HIV, and 102 healthy controls, the hypothesis was tested that lower serum albumin levels would predict larger WMH volumes and worse cognitive performance irrespective of diagnosis." (PMID 38260299, 2024).